STAT3 (signal transducer and activator of transcription 3)
Diseases named in the same sentence as STAT3 in open-access papers (continued):
Sharing a sentence is not in itself a finding about the gene and the disease.
colon carcinoma (continued). "Evidence so far suggested that BCAR4 inhibited miR-665 expression and further promoted STAT3 expression, this signaling cascade was essential to colon cancer cells survival, self-renewal and migration." (PMID 30962766, 2019). "In colon cancer, IL-6 is known to be secreted by stromal fibroblasts, several types of immune cells, and by parenchymal cancer cells to activate STAT3 signaling, thereby mediating tumor-promoting effects." (PMID 30804456, 2019). "Stattic disrupted the activation of STAT3 in a time‐ and dose‐dependent manner, resulting in decreased IL‐8 expression, suggesting a role of STAT3 for IL‐8 expression in colon cancer cell with less ZNF143." (PMID 30933430, 2019). "Here we employed human recombinant IL-6 to activate the IL-6/STAT3 pathway and found that it promotes colon cancer stemness in an FRA1-dependent manner." (PMID 30804456, 2019). "In agreement with enhanced STAT3 activation, cell invasion assays showed that the invasion of colon cancer cells was significantly increased when they were cultured with CM from tRXRα-BMDMs or co-cultured with THP-1 cells expressing tRXRα but not RXRα." (PMID 30931933, 2019). "Given our previous observations that IL11 signaling confers potent activation of STAT3 in gastrointestinal cancer cells, we next examined the effects of bazedoxifene on cytokine‐stimulated human gastric and colon cancer cells." (PMID 30885958, 2019). "Subsequently, a phase III trial of napabucasin showed prolonged survival of phosphorylated STAT3 positive patients in advanced colon cancer." (PMID 31137841, 2019). "When the STAT signaling pathway is constitutively active in tumors, like in breast and colon cancer, STAT3 has also been shown to transcriptionally induce HSP27 expression." (PMID 31861612, 2019). "ALO induces cell-cycle arrest and apoptosis in HCT116 human colon cancer cells via cosuppression of Akt and signal transducer and activator of transcription 3 (STAT3) signaling pathways." (PMID 31534865, 2019). "In this connection, we have previously shown that cytokine-associated STAT3 can bind to, and activate, the promoter of the REG Iα gene in gastric and colon cancer cells." (PMID 31780871, 2019). "As expected, in ALDH+ colon cancer cells, miR-665 was down-regulated but STAT3 and p-STAT3 was up-regulated." (PMID 30962766, 2019). "The STAT3–VEGF pathway is essential for colon cancer development; adiponectin can reduce mRNA VEGF and signal transducer and activator transcription 3 phosphorylation (STAT3)." (PMID 30626010, 2019). "Our team recently identified the first HSP110 inhibitors that block interaction with STAT3 and that effectively limit colon cancer progression in mouse models; we plan to bring these to the clinic within the next few years." (PMID 31861612, 2019). "Incremental expression of proinflammatory cytokines such as NF-κB and TNF-α and overactivation of IL-6/STAT3 passage have been well determined to exercise definitive implication in the pathogenesis of UC and colon cancer." (PMID 31772601, 2019). "Bazedoxifene inhibits phosphorylation of signal transducer and activator of transcription 3 (p-STAT3) and its nuclear translocation induced by IL-11 in colon cancer cells." (PMID 30736824, 2019). "In summary, CDCs from colon cancer cells can promote proliferation of themselves by shortening mitosis duration and activating STAT3." (PMID 31402975, 2019). "IL-6 also promotes DNA methylation of the promoter-bound STAT3, leading to a decrease in STAT3 DNA binding in human colon cancer cells, or of the Foxp3 gene, thus influencing regulatory T cell development." (PMID 31114509, 2019). "Although further studies are needed, STAT3 is considered to be a promising CSC target in colon cancer." (PMID 31137841, 2019). "Neutralization of IL-6 activity by anti-IL-6 antibody diminished its effect on inducing STAT3 activation in CT26 cells and their invasion activity, revealing a role of IL-6 in STAT3 activation and colon cancer cell growth." (PMID 30931933, 2019).
colon carcinoma (continued). "It is characterized by the activation of Stat3 in mucosal immune and epithelial cells, with a subsequent colonic mucosal Th17 response that induces robust colonic tumors." (PMID 29687353, 2018). "We showed that IL-6 induced EMT, which promotes colon cancer progression, and that STAT3 phosphorylation was involved in this pathway." (PMID 30308035, 2018). "Knockdown of Jab1/COPS5 significantly induced reduction of unphosphorylated Stat3 DNA-binding activity and Stat3 target genes, but nuclear Stat3 level was found increased in human colon cancer cell." (PMID 29535627, 2018). "As expected, colon tumors showed enhanced STAT3 phosphorylation compared to the normal epithelium, and interestingly, STAT3 phosphorylation was reduced in tumors from p38α‐ΔMC mice compared to WT mice (Fig EV1F)." (PMID 29907597, 2018). "We found that IL-6 induced EMT in colon cancer cells and that STAT3 phosphorylation was involved in this process." (PMID 30308035, 2018). "Upon treatment with IL-6, the 2 colon cancer cell lines showed decreased levels of E-cadherin and increased levels of phosphorylated STAT3, N-cadherin, SNAI1, and vimentin." (PMID 30308035, 2018). "miR‐181b expression interacted with STAT3 phosphorylation in a positive feedback loop in colon cancer cells via regulating PIAS3 expression." (PMID 30054984, 2018). "Nuclear JAB1 positively regulated unphosphorylated STAT3 DNA-binding activity through protein–protein interaction in the human colon cancer cell line Colo205." (PMID 29914167, 2018). "In the present study, we explored the relationship between miR‐181b (miR‐181b‐5p), PIAS3 and STAT3, and investigated the function of miR‐181b/PIAS3/STAT3 axis on the Warburg effect and xenograft tumour growth of colon cancer." (PMID 30054984, 2018). "Promoter-bound STAT3 can also be methylated at Lys140 in an IL-6-dependent manner by the histone methylase SET9 in human colon cancer cells, and this modification appears to reduce STAT3 binding to DNA, consequently reducing target gene transcription." (PMID 29728695, 2018). "In western blot analysis, IL-6-induced phosphorylated STAT3 signals were faint in the metformin-treated colon cancer cell lines." (PMID 30308035, 2018). "In accordance with our findings, it has been previously determined that excessive IL-22 production leads to tumor growth in colon cancer as well as apoptosis inhibition through STAT3 activation." (PMID 30235866, 2018). "Here the authors identify TRIM27 as a positive regulator of IL-6-induced STAT3 activation through the formation of JAK1-STAT3 complex, thus impacting inflammation-induced colon cancer development." (PMID 30143645, 2018). "In summary, our data has revealed that pro-inflammatory cytokine IL-22 enhances aerobic glycolysis through a STAT3/c-Myc/HK2 signaling pathway in colon cancer cells." (PMID 28445985, 2017). "To do this we first compared IL-6 treated DLD1 derived STAT-3null A4 colon cancer cells versus STAT-3 reconstituted A4 cells." (PMID 28819304, 2017). "STAT3 is a known driver of oncogenesis and indeed, activation of STRA6 signaling was demonstrated to promote tumor progression in a STAT3-dependent manner using a xenograft model of colon cancer." (PMID 28689994, 2017). "Distinct CREB and STAT3 expression patterns were observed in the colon cancer cell lines, indicating that CREB protein expression is inversely correlated with that of STAT3 in colon cancer." (PMID 28725043, 2017). "Another recent study looking at human colon cancer cell lines, confirmed the critical role for the IL-6/STAT3 pathway in enabling TNFR2 upregulation." (PMID 29163543, 2017). "In colon cancer, interleukin-6 (IL-6) is a tumor-promoting factor by inducing neoplastic cell proliferation through activation of the STAT3 oncogene in dysplastic epithelial cells, and its levels correlates with tumor size." (PMID 28448444, 2017).
colon carcinoma (continued). "STAT3 expression in NK cells from patients with gastric, sigmoid, and colon cancer was decreased similar to the expression of c‐kit and c‐myc oncogenes." (PMID 28695716, 2017). "STAT3 acts as an oncogenic tumor marker in prostate and colon cancer tissues, where it mediates hyperplasia and neoplastic transformation." (PMID 28467474, 2017). "Pro-inflammatory cytokine IL-22 was found to enhance aerobic glycolysis through a STAT3/c-Myc/HK2 signaling pathway in colon cancer cells." (PMID 28445985, 2017). "Accordingly, increased expression of additional STAT3 target genes critically involved in colon cancer progression, i.e., cytokine CCL-2 and the oncogene Myc, was detected in Sdc1-KO tumors (middle, right, 4D)." (PMID 28350804, 2017). "Previous studies have indicated that STAT3 is necessary for the maintenance of colon cancer–initiating cells." (PMID 29254202, 2017). "Previous studies have shown that inflammation-induced Jak-STAT3 signaling triggers the ubiquitination of DICER1 in cytoplasm by CUL4A to promote the development of colon cancer." (PMID 28420424, 2017). "We demonstrated that LY5 inhibited constitutive Interleukin-6 (IL-6)-induced STAT3 phosphorylation, STAT3 nuclear translocation, decreased STAT3 downstream targeted gene expression and induced apoptosis in liver and colon cancer cells." (PMID 26883202, 2016). "We have previously shown that Caco-2D299G undergo EMT, an important biologic process in colon cancer development and progression, via STAT3." (PMID 27271572, 2016). "After treatment with LY5 for 24 hours, LY5 also inhibited persistent STAT3 phosphorylation and induced cleaved capase-3, a hallmark of apoptosis, in SW480 and DLD1 colon cancer cells." (PMID 26883202, 2016). "Signal Transducer and Activator of Transcription 3 (STAT3) is persistently activated in human liver and colon cancer cells and is required for cancer cell viability, survival and migration." (PMID 26883202, 2016). "Although the signaling pathway for IL-32θ in colon cancer has yet to be revealed, it has been shown that IL-32θ inhibits the transcriptional activity of STAT3." (PMID 26824417, 2016). "It has been shown that constitutive STAT3 activity in both breast and colon cancer contributes to enhanced cell proliferation and metastasis." (PMID 27259262, 2016). "We found that TSLP activated MAPKs (JNK and p38) and STAT5, but, interestingly, down-regulated phosphorylation of STAT3 in colon cancer cells." (PMID 26919238, 2016). "In this study, we evaluated the inhibitory efficacy of LY5 in liver and colon cancer cells with persistent STAT3 signaling." (PMID 26883202, 2016). "As an example, IL-32γ enhances TNF-α-induced cell death in cases of colon cancer and inhibits the growth of cancer cells by blocking the NF-κB and STAT3 pathways." (PMID 26824417, 2016). "Constitutive activation of signal transducer and activator of transcription 3 (STAT3) contributes to the maintenance of colon cancer and colon cancer-initiating cells." (PMID 26824417, 2016). "We evaluated the inhibitory effects of LY5 on constitutive and inducible STAT3 phosphorylation and the expression of its downstream target genes in colon cancer cells and liver cancer cells." (PMID 26883202, 2016). "Regulation of the IL-6/STAT3 pathway by p38α impinges upon tumor cell proliferation and survival in mouse models of colon cancer." (PMID 25890501, 2015). "Next we assessed phosphorylated STAT3 (pSTAT3) staining as a marker of activated STAT3 in the primary human colon cancer samples." (PMID 28781374, 2015). "Our results extend this observation and suggest an important role for p38α in the regulation of IL-6/STAT3 signaling in human colon tumors." (PMID 25890501, 2015).
colon carcinoma (continued). "It was reported that Hes1 activates signal transducers and activators of the transcription 3 (STAT3) pathway, and that STAT3 controls MMP1 expression in colon cancer cells." (PMID 26650241, 2015). "In our previous studies, the curcumin analog GO-Y030 inhibited β-catenin in the mouse colonic epithelium, inhibited STAT3 phosphorylation in colon cancer stem cells, and inhibited the growth of colon cancer stem cell xenografts in nude mice." (PMID 25331984, 2015). "There is good evidence that IL-6 family cytokines (IL-11 and IL-6) and STAT3 signaling are important for the survival and proliferation of colon tumor cells in mouse models." (PMID 25890501, 2015). "STAT3 is activated (persistent phosphorylation of STAT3) in many human pancreatic and colon cancer cells." (PMID 25961376, 2015). "Together these results demonstrate that upon co-culture with cancer cells ADSCs can activate the JAK2/STAT3 pathways in both breast and colon cancer cells via induced IL-6 expression." (PMID 25797257, 2015). "IL-22 was reported to induce REG Iα transcription via STAT3 activation in human colon cancer cells and to induce Reg I and Reg II in NOD mouse islets." (PMID 25767811, 2015). "We hypothesized that the JNK/STAT3-signaling pathway which is one of the main mechanisms activated by leptin and associated with excess proliferation and inhibition of apoptosis plays a role in the obesity-related mitochondrial dysfunction observed in colon cancer." (PMID 26472027, 2015). "Agreed with the inhibition of STAT3, nucleus translocation of phosphorylation of STAT3 was inhibited by (E)-4-(3-(3,5-dimethoxyphenyl)allyl)-2-methoxyphenol in both colon cancer cells." (PMID 26474284, 2015). "We found that (E)-4-(3-(3,5-dimethoxyphenyl)allyl)-2-methoxyphenol untreated colon cancer cells showed highly constituted activation of STAT3 in both colon cancer cells." (PMID 26474284, 2015). "We conclude that the JNK/STAT3-signaling pathway induced by leptin is indeed involved in the mitochondrial dysfunction related to obesity in colon cancer cells." (PMID 26472027, 2015). "Our findings suggest that HES1 regulate MMP14 expression through up-regulating STAT3 activity in colon cancer cells." (PMID 26650241, 2015). "To determine the relationship between STAT3 or NF-κB activity and colon cancer cell growth inhibitory effect of (E)-4-(3-(3,5-dimethoxyphenyl)allyl)-2-methoxyphenol, we transfected the cells with STAT3 siRNA or p50 siRNA using a transfection agent." (PMID 26474284, 2015). "Our results provide the new evidence for the MEK inhibition can increase the expression and activation of STAT3 in K-Ras mutant pancreatic and colon cancer cells." (PMID 25961376, 2015). "STAT3 and NF-κB cooperate to promote the development and progression of colon cancer, and thus prevent cell death through inhibition of the extrinsic apoptotic pathway which is activated upon binding of extracellular ligands to cell-surface DRs." (PMID 26474284, 2015). "TFF3 has been previously reported to increase phosphorylation (Tyr705) of STAT3 in colon carcinoma cell lines." (PMID 25266665, 2014). "In murine models of colon cancer, IL-6 increases the number and size of tumors, and IL-6 signaling through STAT3 promotes the growth and survival of tumor cells." (PMID 25478789, 2014). "Previously, IL-6 has been shown to activate STAT3 in colon cancer through phosphorylation on the tyrosine 705 residue." (PMID 24098947, 2013). "We demonstrate IL-6-mediated activation of STAT3 occurs in conjunction with the phosphorylation of RKIP in vitro in human colon cancer cells." (PMID 24098947, 2013). "Compounds like CPA-1, CPA-7 can disrupt STAT3 ability to bind DNA leading to apoptosis in STAT3 dependent human breast and colon cancer cell lines." (PMID 24308725, 2013). "The most famous STAT3 activator, IL-6, is widely recognized to play an inflammation-related role in colon cancer." (PMID 23379788, 2013).
colon carcinoma (continued). "The present study demonstrated the role of reactive oxygen species (ROS) in the induction of AKT regulation by cisplatin through the activation of JAK2/STAT3 at the transcriptional level in colon cancer cells." (PMID 23426872, 2013). "Cryptotanshinone inhibited STAT3 activity in a dose-dependent manner in HCT 116 colon cancer cells with an IC50 value of 4.6 μM." (PMID 24308725, 2013). "In summary, this study examines for the first time, the expression profile of RKIP, pRKIP and STAT3 in Stage II colon cancer." (PMID 24098947, 2013). "Our data are in agreement with observations that JAK/STAT3 signaling contributes to the viability of CC cells in vitro, a relevant finding since abnormal activation of this pathway is detected in primary colon cancers." (PMID 24023824, 2013). "The new sequences were tested for their ability to induce cell death in an IFNγ-sensitive, active-STAT3-dependent colon carcinoma cell line." (PMID 22423663, 2012). "For these reasons, we analysed in colon cancer cells the expression of STAT3 protein and the phosphorylation of STAT3 after clofibrate and AS601245 treatments." (PMID 22619672, 2012). "The purpose of the research is to investigate the roles of Jak-STAT3 signaling pathway in bufalin-induced apoptosis in colon cancer SW620 cells." (PMID 23110625, 2012). "In conclusion, our study demonstrates that bufalin induces apoptosis in colon cancer cells through the inhibition of the Jak-STAT3 pathway." (PMID 23110625, 2012). "For example, in the colon carcinoma cell line SW 480, the constitutive activation of STAT3 contributes to cell survival; its inhibition by STAT3-decoy ODN induces cell death." (PMID 21486470, 2011). "The findings of the present paper indicate that active STAT3 interacts with NF-κB in the colon-carcinoma cell line SW 480, as shown by the presence of NF-κB in STAT3-decoy ODN pull-downs and by reduced NF-κB transcriptional activity." (PMID 21486470, 2011). "A previous report, using HT-29 colon carcinoma cells in mouse xenograft experiments, showed a reduction in tumor size for cells stably expressing a similar Stat3 dominant negative form compared to parental HT-29 tumors." (PMID 21595927, 2011). "We examined the inhibitory effects of GO-Y030 in the inhibition of STAT3 in colon cancer stem cells." (PMID 21694723, 2011). "Persistent activation of signal transducers and activators of transcription 3 (STAT3) is commonly detected in many types of cancer, including colon cancer." (PMID 21694723, 2011). "To explore the inhibition of STAT3 in colon cancer stem cells, we examined the inhibitory effects of a newly developed curcumin analogue, GO-Y030." (PMID 21694723, 2011). "The in vivo results are consistent with the in vitro cancer stem cell data, indicating that GO-Y030 is a potent inhibitor for the STAT3 pathway to suppress tumour growth of colon cancer stem cells in mouse models in vivo." (PMID 21694723, 2011). "Our results observed that ALDH+/CD133+ colon cancer cells expressed higher levels of phosphorylated STAT3 than ALDH-negative/CD133-negative colon cancer cells, suggesting that STAT3 is activated in colon cancer stem cells." (PMID 21694723, 2011). "Another study also provided evidence that suppression of invasion and metastasis by STAT3 knockdown depended on VEGF down-regulation of colon cancer cells." (PMID 21991388, 2011). "This study extends previous research by using both ALDH and CD133 together as markers for colorectal stem cells from colon cancer cell lines and examines STAT3 phosphorylation in these cancer stem cells." (PMID 21694723, 2011). "The levels of STAT3 phosphorylation and the effects of STAT3 inhibition by a newly developed curcumin analogue, GO-Y030, that targets STAT3 in colon cancer stem cells were examined." (PMID 21694723, 2011). "GO-Y030 also reduced STAT3 downstream target gene expression and induced apoptosis in colon cancer stem cells." (PMID 21694723, 2011).